BPTF (bromodomain PHD finger transcription factor)
Diseases named in the same sentence as BPTF in open-access papers (continued):
Sharing a sentence is not in itself a finding about the gene and the disease.
triple-negative breast carcinoma (3 papers, 2022 to 2025). An invasive breast carcinoma which is negative for expression of estrogen receptor (ER), progesterone receptor (PR), and human epidermal growth factor receptor 2 (HER2). "Elevated BPTF copy number was significantly associated with increasing patient age and tumor grade and observed in both ER-positive and triple-negative breast cancer (TNBC) subtypes." (PMID 36530982, 2022). "On the other hand, BPTF targeting with the bromodomain inhibitor bromosporine has been reported to exert anti-tumour effects against triple-negative breast cancer cells." (PMID 40633141, 2025). "PRPF4B and BPTF act as transcriptional modulators and are described as part of the complex gene network that defines the migratory program of triple-negative breast cancer cells." (PMID 37444610, 2023).
acute megakaryoblastic leukemia (2 papers, 2021 to 2026). Acute megakaryoblastic leukemia (AMKL) is a form of acute myeloid leukemia (AML) that occurs predominantly in childhood and particularly in children with Down syndrome (DS-AMKL). "In particular, the NUP98::BPTF fusion has been detected in a patient with acute megakaryoblastic leukemia." (PMID 41419605, 2026). "Moreover, a NUP98-BPTF gene fusion in which a C-terminal chromatin recognition module of BPTF is fused to the N-terminal moiety of NUP98 has been identified in primary refractory acute megakaryoblastic leukemia (AMKL) that contributes to refining the NUP98 rearrangement subgroup of pediatric AMKL." (PMID 34736517, 2021).
clear cell renal cell carcinoma (2 papers, 2023). "The down-regulated METTL14 in renal clear cell carcinoma can accumulate bromodomain PHD finger transcription factor (BPTF) and cause distant lung metastasis through chromatin remodeling." (PMID 36941564, 2023). "In the clear cell renal cell carcinoma model, down-regulated METTL14 induced the overexpression of BPTF." (PMID 36967443, 2023).
colon cancer (2 papers, 2021 to 2023). "The self-renewal and the stemness of colon tumor-initiating cells is enhanced by circCTIC1 by upregulating BPTF-dependent c-Myc expression in colon cancer." (PMID 34168984, 2021).
developmental delay (2 papers, 2020 to 2021). "Patient 287 with c.7927‐1G > A in the BPTF gene (NM_182641.3) showed intrauterine growth restriction, global developmental delay, facial dysmorphism, facial asymmetry, clinodactyly, which was considered as Silver‐Russell syndrome." (PMID 32901917, 2020).
medulloblastoma (2 papers, 2016 to 2026). A malignant, invasive embryonal neoplasm arising from the cerebellum. "Medulloblastoma, a malignant pediatric brain tumor, involves the bromodomain PHD finger transcription factor (BPTF) protein, an epigenetic regulator linked to tumor progression." (PMID 42109336, 2026). "Thus, Sanguinarine chloride emerged as the most promising BPTF inhibitor for potential anti-medulloblastoma therapy." (PMID 42109336, 2026).
periodontitis (2 papers, 2020 to 2022). An acute or chronic inflammatory process that affects the tissues that surround and support the teeth. "In subjects with well-controlled T2DM plus DL plus periodontitis versus HS, there were 3 DEG genes (BPTF, PDE3B, and FN1)." (PMID 36233348, 2022).
benign prostatic hyperplasia (1 paper, 2025). A non-cancerous nodular enlargement of the prostate gland. "BPTF staining was elevated in PCa samples with lymph node metastasis and in CRPC compared to benign prostatic hyperplasia (BPH) and primary PCa." (PMID 41381516, 2025).
brain ischemia (1 paper, 2024). Diminished or absent blood supply to the brain caused by obstruction (thrombosis or embolism) of an artery resulting in neurologic damage. "These proteins include BPTF and MEF2C, which govern microglial homeostatic responses; MEF2A, which promotes autophagy; and ZEB1, which mediates protective effects after brain ischemia (Set 2)." (PMID 38178204, 2024).
endometrial cancer (1 paper, 2024). Primary or metastatic malignant neoplasm involving the endometrium (mucous membrane that lines the endometrial cavity). "Gene loci associated with endometrial cancer, including BPTF and MDN1, were upregulated in uterine epithelial cells after estrogen treatment." (PMID 39872660, 2024).
esophageal squamous cell carcinoma (1 paper, 2021). Esophageal squamous cell carcinoma (ESCC) is a type of esophageal carcinoma (EC) that can affect any part of the esophagus, but is usually located in the upper or middle third. "In esophageal squamous cell carcinoma (ESCC), lncRNA NMR methylated by NSUN2 combines with the chromatin regulator BPTF to promote the expression of MMP3 and MMP10 via the ERK1/2 pathway; thus, promoting the progression of ESCC." (PMID 34777473, 2021).
liver cancer (1 paper, 2019). An epithelial or non-epithelial malignant neoplasm that arises from the liver. "Mechanistically, BPTF-activated human telomerase reverse-transcriptase (hTERT) expression and promoted stemness, proliferation, tumor growth, and metastasis associated with liver cancer." (PMID 31769422, 2019). "BPTF expression was associated with promoting resistance to BRAF inhibitors in melanoma, and its knockdown sensitized liver cancer cells to chemotherapeutic drugs." (PMID 31769422, 2019).
Macrocephaly (1 paper, 2023). Occipitofrontal (head) circumference greater than 97th centile compared to appropriate, age matched, sex-matched normal standards. "Individuals with pathogenic variants in SMARCA1 are phenotypically distinct in comparison to BPTF and SMARCA5 NDDs, as suggested primarily by the high penetrance of macrocephaly." (PMID 37841849, 2023).
myeloma (1 paper, 2021). "Six TFs (CXXC1, BPTF, MAZ, KLF13, CBFB and RFX5) were identified as showing higher connectivity in all myeloma subgroups compared to ND PC, thus exemplifying the process of existing TF ‘re-wiring’ in MM." (PMID 34521827, 2021).
neuropathies (1 paper, 2020). "At least TUBGCP6, SYNE1, BPTF, KIDINS220, MYO5A, VPS13B, TBC1D24) are known to contain mutations causing various neuropathies." (PMID 32561887, 2020).
Nicolaides-Baraitser syndromes (1 paper, 2023). "Given that a clinical continuum is observed in Coffin-Siris and Nicolaides-Baraitser syndromes depending on which BAF encoding gene is mutated, it is not unusual to consider that SMARCA1, SMARCA5, and BPTF NDDs may also align along a clinical spectrum." (PMID 37841849, 2023).
pancreatic ductal adenocarcinoma (1 paper, 2022). An infiltrating adenocarcinoma that arises from the epithelial cells of the pancreas. "In the present manuscript, we described the role of BPTF during tumour pancreatic ductal adenocarcinoma progression and in response to gemcitabine treatment, a gold standard treatment in this tumour type." (PMID 35326669, 2022). "We show that BPTF is a therapeutic target in pancreatic ductal adenocarcinoma due to its strong effect on proliferation and in response to gemcitabine." (PMID 35326669, 2022). "Through different genetic approaches, we reduced BPTF levels in a panel of pancreatic ductal adenocarcinoma cell lines." (PMID 35326669, 2022).
prostate adenocarcinoma (1 paper, 2021). "Through the TCGA database analysis, RBBP4/7 and BPTF is simultaneously overexpressed in ESCA, LIHC, STAD etc. and downregulated in KIRC, KICH, kidney renal papillary cell carcinoma (KIRP) and prostate adenocarcinoma (PRAD)." (PMID 34736517, 2021). "According to TCGA database, BPTF is upregulated in STAD, ESCA, LIHC, LUAD and downregulated mainly in kidney Chromophobe (KICH), thyroid carcinoma (THCA), kidney renal clear cell carcinoma (KIRC), prostate adenocarcinoma (PRAD), etc.." (PMID 34736517, 2021).
sarcoma (1 paper, 2025). A usually aggressive malignant neoplasm of the soft tissue or bone. "Notably, several SWIFT domain-interacting TFs represented top dependencies in the cancer cell lines in which interactions were identified such as BPTF and TERF2vin ES cells and YY1 and MAX in U2OS sarcoma cells." (PMID 40766474, 2025).
T-cell lymphoma (1 paper, 2023). "Similarly, bromodomain PHD finger transcription factor (BPTF) activates the MAPK pathway and is coexpressed with CRAF in T-cell lymphoma tissues." (PMID 38111008, 2023).
cancer (45 papers, 2010 to 2025). A tumor composed of atypical neoplastic, often pleomorphic cells that invade other tissues. "Although it is an indisputable fact that transcription factors are intimately associated with cancers, little is known about the roles of BPTF in cancers." (PMID 26418899, 2015). "Although BPTF has previously been reported to promote the progression of multiple cancer types by regulating c-Myc activity, our study shows that BPTF primarily upregulates the AR transcriptional program in PCa." (PMID 41381516, 2025). "An example of this was the bromodomain PHD finger transcription factor (BPTF), which is thought to be overexpressed in multiple types of cancer, with poor prognosis." (PMID 40783120, 2025). "Analysis of transcriptomic datasets from public databases revealed that BPTF expression levels in PCa cell lines are comparable to those in other cancer cell lines." (PMID 41381516, 2025). "BPTF was previously identified as a tumor-promoting factor in several cancer types, including lung, liver, ovarian, gastric, colorectal, and brain cancers." (PMID 36674511, 2023). "In liver tumors, BPTF promotes tumor growth by modulating hTERT signaling and cancer stem cell traits." (PMID 36674511, 2023). "The negative regulation of PIK3R3 by BPTF was lost from normal to cancer, which was in accordance with the over-expression of PIK3R3 in cancer." (PMID 35421923, 2022). "Aberrantly high levels of the BPTF/NURF complex are supposed to promote cancer immune escape by impacting multiple types of immune cell activity." (PMID 34736517, 2021). "For example, BPTF promotes the growth of cancer cells by regulating the expression of human telomerase reverse transcriptase, and its high expression is associated with advanced malignancy." (PMID 34335688, 2021). "Previous studies have reported that BPTF is an essential epigenetic regulator in various cancers, but little is known about its effect in RCC, especially with respect to metastasis." (PMID 33664855, 2021). "Using well-characterized and validated antibodies against BPTF, we found several molecular species with unexpected electrophoretic mobilities in human cancer cells." (PMID 31498079, 2019). "For other potential candidates such as BPTF, the correlation with metastasis-free survival added evidence that these candidate genes are likely involved in cancer metastasis." (PMID 31278301, 2019). "In humans, genetic alterations in BPTF have been reported in several types of cancer and a role of BPTF in transcriptional regulation by c-MYC has been demonstrated, in agreement with its chromatin-binding function." (PMID 31498079, 2019). "The nucleosome-remodeling factor BPTF has been shown to be present in various cancers with different metastatic potentials." (PMID 30558204, 2018). "However, BPTF can be linked with pro- or anti-metastatic roles, which may mean changes in its expression are indirect, that it has cell type specific effects, or that it may act in human cancer pathogenesis via multiple mechanisms." (PMID 30558204, 2018). "To gain insight into the role of the c-MYC:BPTF axis in human cancer, we analysed public omics data sets." (PMID 26729287, 2016). "Here, the authors show that c-MYC requires the chromatin reader BPTF to activate its transcriptional program and promote tumour development in vivo, suggesting that BPTF is a potential target for cancer therapy." (PMID 26729287, 2016). "Immunohistochemical staining showed that lung tumor tissues had much higher expression of BPTF than their adjacent non-cancer tissues." (PMID 26418899, 2015). "To address this question, we individually knocked down H2A.Z, WDR5, and BPTF in LD611 cancer cells and looked at the expression of H2A.Z target genes." (PMID 24279307, 2013). "We also provide evidence in support of the engagement of H3K4me2/me3 and WDR5/BPTF in H2A.Z-induced cancer pathogenesis." (PMID 24279307, 2013).
cancer (continued). "Notably, bromodomain PHD-finger TF (BPTF) is an attractive target for certain cancers, considerably correlating with the expression levels of EMT markers (Vimentin and E-cadherin), which can promote EMT progression in CRC." (PMID 40109856, 2025). "MYC interacts with BPTF to induce MDR in cancer cells through upregulation of ABC transporters." (PMID 37450923, 2024). "Therefore, BPTF inhibition has arisen as a promising strategy to combat cancer through epigenetic regulation of the c-Myc oncogenic pathway." (PMID 36674511, 2023). "Taken together, systematic analysis of NUP98-NSD1-bound proteome identified the ISWI family protein SMARCA5 (and its cancer co-dependent partners BPTF and NUP188) as stable interactors and revealed their potential functional co-operation in transcriptional regulation of stem cell differentiation." (PMID 35073946, 2022). "BPTF is suggested to be a pan prognostic marker in various cancers." (PMID 34736517, 2021). "Genetic disorders of the BPTF gene are commonly seen in various cancer tumors." (PMID 34736517, 2021). "Recent studies have indicated that BPTF promotes tumor cell growth in several types of cancers." (PMID 33232269, 2020). "Indeed, our study is the first to report that circ-BPTF expression is increased in BCa, promoting progression of this cancer." (PMID 30103209, 2018). "Additionally, it has been shown that cancer cells upregulate heparanase through activation of bromodomain PHD finger transcription factor (BPTF), leading to reduced NCR-HSPG interaction, which results in dampened NK cell response." (PMID 30197623, 2018). "Given the repressive function of its Drosophila homolog (E(Bx)) in Jak/STAT signaling, we hypothesize that BPTF could be involved in human cancer metastasis, in part, by suppressing Jak/STAT signaling." (PMID 30558204, 2018). "Among the genes required for growth was also BPTF, a cancer gene less studied in CRC." (PMID 30202008, 2018). "Bromodomain Adjacent to Zinc finger domain 1B (BAZ1B), Bromodomain PHD finger Transcription Factor (BPTF), Bromodomain containing 4 (BRD4) and CHD4 are key components of various epigenetic complexes implicated in cancer growth, progression and/or metastasis formation." (PMID 27779108, 2016). "BPTF acts as an oncogenic protein in various cancer types, but its role in PCa remains unclear." (PMID 41381516, 2025). "Also, BPTF knockdown affected the EMT signaling pathway—a critical regulator of cancer stemness." (PMID 36674511, 2023). "All these researches indicate that BPTF may be a cancer-promoting protein." (PMID 26418899, 2015). "Through multidisciplinary techniques, our findings establish targeting BPTF with PROTACs as a promising approach to overcome immune evasion of HCC from NK cells and provide a new strategy to enhance NK cell-based cancer immunotherapy." (PMID 39935175, 2025). "Thereinto, SOX9 activation was proved to repress miR-203a transcription by binding to miR-203a promoter, while BPTF has been identified to promote HCC growth and enhance cancer stem cell traits." (PMID 37794386, 2023). "The bromodomain PHD finger transcription factor (BPTF) plays a significant role in the invasion and progression of cancers." (PMID 37284313, 2023). "The positive regulation of PPM1L by BPTF was lost from normal to cancer, and meanwhile the expression of PPM1L was found to be decreased in cancer, which is consistent with the regulation change." (PMID 35421923, 2022). "The results still showed that the expression of BPTF, VEGF and CD144 in cancer tissues was higher than that in para-cancer tissues." (PMID 36529788, 2022). "The results showed that compared with the adjacent tissues, BPTF, VEGF, VE cadherin and CD31 were highly expressed in cancer tissues." (PMID 36529788, 2022). "The positive regulation of NKX6.3 by BPTF was reversed from normal to cancer, and consistently, the decreased expression of NKX6.3 was observed in cancer." (PMID 35421923, 2022).
cancer (continued). "In the COSMIC database, 78, 114, 113, and 83 studies confirmed the correlation between HNRNPA2B1, BPTF, LRRK1, and PUM1 with cancer, respectively." (PMID 32300588, 2020). "KAT6B-ADK (n = 6), BPTF-PITPNC1 (n = 5), and NCOA3-EYA2 (n = 5) were the most frequent fusions among the common cancer types examined in our study." (PMID 30760718, 2019). "In culture, BPTF suppresses direct natural cytotoxicity receptor (NCR) mediated NK cell cytolytic activity to mouse and human cancer cell lines, demonstrating conserved functions." (PMID 28969075, 2017). "The BPTF gene is frequently amplified and overexpressed in a variety of cancers including breast, lung, and brain, though how NURF functions in cancer biology is just beginning to be understood." (PMID 28969075, 2017). "Our findings uncover BPTF as a crucial c-MYC co-factor required for its biological activity and suggest that the BPTF-c-MYC axis is a potential therapeutic target in cancer." (PMID 26729287, 2016). "BPTF, a subunit of NURF, is well known to be involved in the development of eukaryotic cell, but little is known about its roles in cancers, especially in non-small-cell lung cancer (NSCLC)." (PMID 26418899, 2015). "Wang and colleagues have developed PROTAC 8d, which selectively degrades BPTF, leading to an increase in recognition ligands on HCC cells, thereby enhancing the destruction by NK cells, effectively restoring NK cells' ability to combat cancer." (PMID 39935175, 2025). "In addition, BPTF, SIN3A, CNOT1 and YY1 were highly positively correlated in both pan-cancer and ccRCC datasets." (PMID 33232269, 2020). "Furthermore, after network analysis, EPRS, HNRNPA2B1, BPTF, LRRK1, and PUM1 were demonstrated to have a broad correlation with cancers." (PMID 32300588, 2020). "This revealed a sub-network linking eight transcriptional regulators of which most already have been related to cancer progression, including HDAC2, BPTF, BRF1, TAF11, TCF12, and FOS31,32, but also a prominent role for SMADs that are normally driven by TGF-β33." (PMID 31278301, 2019). "For example, 66.7% (42/63) of putative therapeutic target HAMPs are largely uncharacterized with limited indications about how these genes influence cell biology and cancer, although many of these understudied HAMPs are recurrently altered among cancers, such as BRD9, BRD1, BPTF, and ATAD2." (PMID 30760718, 2019). "The significance of BPTF, and by extension NURF, regulation of HPSE in cancer could have broader implications." (PMID 28969075, 2017). "First, we analysed the expression of BPTF and c-MYC in the Cancer Cell Line Encyclopedia data set." (PMID 26729287, 2016). "In line with the molecular functions of the selected genes modulating transcription (BPTF, DDX21), protein translation (NOLC1, TCOF1), or nuclear import (KPNA2) it is feasible to speculate that restoring their cellular content in cancer cells could facilitate viral production." (PMID 34203557, 2021). "In addition, an analysis of BPTF and HPSE expression in human cancers from the TCGA data sets revealed a highly significant correlation between high BPTF expression and high HPSE expression in several cancer types including breast (see arrow)." (PMID 28969075, 2017).